MIA (MIA SH3 domain containing)
Description:
Elicits growth inhibition on melanoma cells in vitro as well as some other neuroectodermal tumors, including gliomas.
Synonyms: CD-RAP; MIA1
Tractability: Small molecule: a structure with a bound ligand is known. Antibody: UniProt places it where antibodies can reach, with medium confidence; UniProt predicts a signal peptide or a membrane-spanning region; its Gene Ontology location is reachable by antibodies, with medium confidence.
Gene: Protein-coding gene on chromosome 19 (40,768,997 to 40,777,490, forward strand). Ensembl gene ENSG00000261857.
Subcellular location: Secreted
Gene Ontology:
Biological process: extracellular matrix organization
Cellular component: extracellular region
Genetic constraint (gnomAD): Loss-of-function variants: 14 observed, 16.99 expected, observed/expected ratio (o/e) 0.82, 90% interval 0.54 to 1.29. The upper end of that interval is the gene's LOEUF score, 1.29, which puts it in group 5 of 6, group 1 being the genes least tolerant of losing a copy. Missense variants: 158 observed, 180.42 expected, observed/expected ratio (o/e) 0.88, 90% interval 0.77 to 1. Synonymous variants: 55 observed, 68.8 expected, observed/expected ratio (o/e) 0.8, 90% interval 0.64 to 1.
Homologues: Orthologues: chimpanzee MIA (97% identical), macaque MIA (96% identical), dog MIA (88% identical), guinea pig MIA (87% identical), pig MIA (85% identical), rabbit MIA (84% identical), mouse Mia (82% identical), tropical clawed frog mia (64% identical), rat Mia (57% identical), zebrafish mia (56% identical), Drosophila melanogaster Tango1 (23% identical). Paralogues in human: OTOR (41% identical), MIA2 (37% identical), MIA3 (33% identical), CTAGE1 (14% identical), CTAGE15 (12% identical), CTAGE6 (12% identical), CTAGE4 (11% identical), CTAGE8 (11% identical), CTAGE9 (11% identical), SPZ1 (5% identical).
Diseases named in the same sentence as MIA in open-access papers:
MIA is named in the same sentence as 37 diseases in open-access papers, as found by Europe PMC text mining. Sharing a sentence is not in itself a finding about the gene and the disease. The quoted sentences say what the papers report.
melanoma (33 papers, 1999 to 2025). A malignant, usually aggressive tumor composed of atypical, neoplastic melanocytes. "RBPs that were specific to EVs included YBX1, a known prognostic marker for several cancers, which has been linked to melanoma progression by regulating MIA-dependent expression." (PMID 38353833, 2024). "MIA is a secretory protein and has been implicated in the progression of malignant melanoma." (PMID 27050375, 2016). "Overexpression of MIA not only promoted melanoma metastasis but also activated the invasive ability of pancreatic cancer cells." (PMID 38762700, 2024). "Melanoma inhibitory activity/cartilage-derived retinoicacid-sensitive protein (MIA/CD-RAP) is a protein expressed and secreted by chondrocytes and cartilaginous tissues." (PMID 36672165, 2023). "OTOR (otoraplin or MIAL1) and MIA belong to several extracellular SH3DCPs of the melanoma-inhibiting activity (MIA) family, and they contain only one SH3 domain." (PMID 37626864, 2023). "UBE2S was found to be highly expressed in most tumor tissues, while MIA was mainly concentrated in tumor tissues of melanoma (SKCM)." (PMID 37479876, 2023). "S100B, VEGF (vascular endothelial growth factor), IGF-1R (the insulin-like growth factor 1 receptor), Wnt-5a, LDH (lactate dehydrogenase), and MIA (melanoma inhibitory activity) have all been shown to correlate positively with prognosis in CM." (PMID 35982458, 2022). "A previous report revealed that SOX10 transactivates MIA expression through its promoter to induce invasive capacity of melanoma cells." (PMID 30642390, 2019). "We also identified 2 differentially expressed genes from the melanoma inhibitory activity (MIA) family: MIA and otoraplin (OTOR)." (PMID 28974924, 2018). "Melanoma inhibitory activity (MIA) belongs to the MIA gene family together with the homologous genes MIA2 and MIA3." (PMID 27050375, 2016). "Melanoma inhibitory activity (MIA) gene family members include MIA, MIA2, and Transport and Golgi organization protein 1 (TANGO)." (PMID 27145272, 2016). "Recent reports have revealed that MIA expression is induced by binding of SRY (sex-determining region Y)-box 10 (SOX10) to the MIA promoter region in malignant melanoma." (PMID 27050375, 2016). "MIA expression has also been observed in malignant melanoma, gastric cancer, pancreatic cancer, breast cancer, chondrosarcoma, glioma, and OSCC." (PMID 27145272, 2016). "The melanoma inhibitory activity (MIA) gene family includes MIA, MIA2, Transport and Golgi organization protein 1 (TANGO), and otoraplin (OTOR)." (PMID 27145272, 2016). "We recently revealed that p54nrb acts as a mediator of MIA/CD-RAP action to promote chondrogenesis and the progression of malignant melanoma." (PMID 24349210, 2013). "MIA/CD-RAP is a small, secreted protein involved in cartilage differentiation and melanoma progression." (PMID 24349210, 2013). "Recently, we identified one highly conserved region in the p54nrb promoter that is necessary for MIA-dependent activation in melanoma." (PMID 24349210, 2013). "Because melanoma cell lines have been shown to have strong p54nrb promoter activity, the regulation of p54nrb via MIA/CD-RAP was shown to involve transcriptional regulation." (PMID 24349210, 2013). "Melanoma inhibitory activity (MIA)/cartilage-derived retinoic acid-sensitive protein (CD-RAP) is secreted from malignant melanoma cells as well as chondrocytes." (PMID 24349210, 2013). "MIA/cadherin-7 interactions were shown to regulate cell-cell adhesion of malignant melanoma cells, influencing their migration." (PMID 21726432, 2011). "The MIA protein, the secreted inhibitor of cell growth, prevents the attachment of melanoma cells to the extracellular matrix, thus promoting invasion and metastazing." (PMID 22649681, 2011). "Deletion or mutation of this site results in a considerable decrease in human MIA promoter activity in melanoma cell lines." (PMID 22649681, 2011).
melanoma (continued). "The constructs with a full-size MIA promoter (1386 bp) and the minimal MIA promoter (493 bp) that is sufficient for maintaining the specific transcription in melanoma cells have been studied." (PMID 22649681, 2011). "It was shown that the constructs containing only MIA promoters have a low transcriptional activity only in melanoma cell lines." (PMID 22649681, 2011). "Expression of MIA is an early event in melanoma development and correlates with tumor progression in vivo." (PMID 19216735, 2009). "Melanoma-derived growth regulatory protein (MIA) (down-regulated in HR) mediates detachment of cells from ECM structures enhancing their migratory potential." (PMID 19878563, 2009). "Given that MIA is predominantly expressed in malignant melanoma, its relationship with AE remains unclear." (PMID 41441218, 2025). "MIA is a melanoma-derived growth regulatory protein that can inhibit the growth of melanoma cells and some other neuroectodermal tumors (including gliomas) in vitro, and it may be an antitumor molecule in melanoma." (PMID 36936375, 2023). "We investigated the S100B and MIA levels in peripheral blood from 176 melanoma patients." (PMID 37373887, 2023). "A small molecule that was discovered using a binding site prediction approach and in vitro fragment screening can disrupt the MIA–FN interaction by binding to a specific pocket on the MIA protein; it can serve as a potential target during future drug development against melanoma." (PMID 37626864, 2023). "In addition, cadherin-7 was identified as a new MIA-binding protein that negatively regulates the expression and activity of MIA, and it plays a role in the migration of melanoma cells during tumor development." (PMID 37626864, 2023). "Additionally, expression of the prominent cartilage matrix proteins type 2 collagen (Col2a1), Aggrecan (Acan), and melanoma inhibitory activity/cartilage-derived retinoic acid-sensitive protein (MIA/CD-RAP) was analyzed." (PMID 26273614, 2015). "Another example for redundancy during chondrogenesis is the mouse deficient for melanoma inhibitory activity/cartilage-derived, retinoic acid–sensitive protein (MIA/CD-RAP), which also does not manifest strong abnormalities." (PMID 25964075, 2015). "Recombinant MIA inhibits melanoma cell growth and cell attachment in vitro." (PMID 21726432, 2011). "In a previous study, we revealed that MIA/CD-RAP acts as a homodimer in malignant melanoma and that AR71 successfully dissociates MIA–MIA homodimers in vitro, as measured by a heterogeneous transition-metal-based fluorescence polarization (HTFP) assay." (PMID 36672165, 2023). "A known MIA/CD-RAP downstream mediator is the Y-box-binding transcription factor 1 (YBX1), which has been described in chondrogenesis and melanoma development." (PMID 36672165, 2023). "MIA and MIA2 are expressed not only in malignant melanoma but also within various malignant tumors, and their expression appears to increase with malignant transformation." (PMID 34441956, 2021). "Under low RA concentration, the expression of cartilage-derived retinoic acid-sensitive protein (CD-RAP), alternatively referred to as melanoma inhibitory activity (MIA), was observed at high levels in melanoma cell lines or cartilaginous cells." (PMID 28500502, 2017). "Regarding other MIA gene family members, TANGO has been suggested as a tumor suppressor in malignant melanoma, colorectal cancer, and hepatoma." (PMID 27145272, 2016). "In agreement with our study in melanoma cells, we revealed that MIA/CD-RAP-dependent modulation of the p54nrb promoter activity is controlled by a conserved 42 bp DNA element." (PMID 24349210, 2013). "Moreover, SOX10 protein levels were inversely correlated with Fbxw7α in melanoma cells, and modulation of Fbxw7α levels regulated the expression of SOX10 and its downstream gene MIA." (PMID 26461473, 2015). "In a recent study in melanoma, we found that YBX1 could transcriptionally regulate MIA/CD-RAP-dependent p54nrb transcription." (PMID 24349210, 2013).
melanoma (continued). "It has been known that the 1.4 kb-long region flanking the 5’-fragment of the MIA gene with respect to the transcription starting site provides the specificity of expression of this gene only in melanoma cells, not in melanocytes." (PMID 22649681, 2011). "The secreted MIA protein is strongly expressed by advanced primary and metastatic melanomas but not in normal melanocytes." (PMID 11027436, 2000). "MIA mRNA was detected in 16 out of 19 melanoma cell lines and in seven out of 16 non-melanoma cell lines after 30 cycles of PCR." (PMID 10576666, 1999). "In previous work we could show that CtBP1 functions as a strong repressor of melanoma inhibitory activity (MIA) expression by negatively regulating MIA promoter activity in malignant melanoma, and that this repressor function requires the TCF binding element in the MIA promoter." (PMID 19216735, 2009). "The MIA gene promoter is of special interest, since this gene, as opposed to the TYR gene, is expressed only in malignant melanoma cells but not in other cells of the melanocyte lineage." (PMID 22649681, 2011).
pancreatic cancer (5 papers, 2005 to 2024). "To determine the functional role of MIA in pancreatic cancer, we first investigated MIA expression in pancreatic cell lines." (PMID 15710044, 2005). "In contrast, in pancreatic cancer tissues, MIA immunoreactivity was moderate in the cancer cells and in tubular complexes in CP-like lesions adjacent to the tumor mass, and in blood vessels and nerve ganglia." (PMID 15710044, 2005). "In the present study, we have further investigated the expression and localization of MIA, and its functional role in pancreatic cancer." (PMID 15710044, 2005). "Immunoblot analysis was employed to evaluate MIA protein levels in pancreatic cancer cell lines." (PMID 15710044, 2005). "To investigate possible mechanisms of MIA overexpression in pancreatic cancer cells, we analyzed whether micro-environmental changes may modulate MIA expression." (PMID 15710044, 2005). "QRT-PCR analysis revealed relatively high MIA mRNA levels in Mia PaCa-2, Panc-1, and SU8686 pancreatic cancer cells compared to the other cell lines." (PMID 15710044, 2005). "The overexpression of miRNA-10a has been observed to down-regulate the transcriptional suppressors and metastatic factors (homeobox transcription factors)—HOX (HOXB1, HOXB2, HOXA1) in various pancreatic cancer cell lines including, PANC-1, CAPAN-1, SUIT-2, KP-2 and MIA PaCa-2." (PMID 39200178, 2024). "The analysis revealed a 42 ± 28-fold increase (p = 0.0013) of MIA mRNA levels in pancreatic cancer tissues compared to the normal pancreas." (PMID 15710044, 2005).
glioma (4 papers, 2011 to 2024). A benign or malignant brain and spinal cord tumor that arises from glial cells (astrocytes, oligodendrocytes, ependymal cells). "Our finding of MIA expression in various NF1-related tumours is consistent with the findings of previous reports that MIA is expressed in glial tumours." (PMID 21726432, 2011). "Melanoma-derived growth regulatory protein (MIA), infrequently expressed in gliomas, can signal slower progression in high-grade glioma." (PMID 38350915, 2024).
breast carcinoma (3 papers, 2016 to 2023). "We also used qPCR to confirm that the MIA mRNA levels were lower in breast cancer cell lines compared with normal breast cells, which gave insights into breast cancer progression and metastasis." (PMID 37842046, 2023). "Serum MIA interacts with extracellular matrix proteins, and its overexpression is also observed in breast cancer and colorectal cancer." (PMID 34722301, 2021).
colorectal cancer (3 papers, 2017 to 2024). A primary or metastatic malignant neoplasm that affects the colon or rectum. "Ultimately, based on our analysis, S100A16 and S100A14 were validated as potential second-class drug targets for HER-positive breast cancer, PDE5A as potential first-class drug targets for colorectal cancer, and MIA as potential second-class drug targets for non-small cell lung cancer." (PMID 38762700, 2024).
chondrosarcoma (2 papers, 2016 to 2023). A malignant cartilaginous matrix-producing mesenchymal neoplasm arising from the bone and soft tissue. "Targeted gene silencing of MIA/CD-RAP with small interfering RNAs led to a significant downregulation of MMP13 expression in the chondrosarcoma cell line SW1353." (PMID 36672165, 2023). "As a possible mediator, we could detect matrix metalloproteinase 13 (MMP13), and the influence of MIA/CD-RAP on MMP13 regulation was analyzed in vitro using SW1353 chondrosarcoma cells and primary chondrocytes." (PMID 36672165, 2023). "In the current study, we suggested a possible regulatory effect on MMP13 mRNA by MIA/CD-RAP via YBX1 in differentiated chondrocytes and SW1353 chondrosarcoma cells." (PMID 36672165, 2023). "To confirm MMP13 regulation by MIA/CD-RAP, we performed an siPOOL-mediated knockdown of MIA/CD-RAP in the human chondrosarcoma cell-line SW1353 and revealed a significant downregulation of MMP13 mRNA after 72 h of siMIA transfection." (PMID 36672165, 2023). "These first results in SW1353 chondrosarcoma cells and isolated chondrocytes displayed the regulation of MMP13 by MIA/CD-RAP and were an important baseline for further investigations." (PMID 36672165, 2023).
lung carcinoma (2 papers, 2012 to 2016). "In the validation analysis, MIA gene family staining was observed frequently in esophageal and lung cancers associated with nodal and/or distant metastasis." (PMID 27145272, 2016). "In particular, cases of ESCC and lung cancer with nodal and/or distant metastases were frequently positive for MIA gene family expression; similarly, lung SCCs were frequently positive for these proteins." (PMID 27145272, 2016). "We also confirmed the significance of MIA gene family expression in ESCC, lung cancer, and cervical cancer." (PMID 27145272, 2016).
atherosclerosis (1 paper, 2020). A disease characterized by the build-up of fatty material and calcium deposition in the arterial wall resulting in partial or complete occlusion of the arterial lumen. "TNFRSF4 is involved in atherosclerosis development and tPA is involved in thrombolysis, while PRSS8, FRalpha, MIA, FUR, CDH3 and HE4 are involved in various cancer processes." (PMID 33066363, 2020).
cervical cancer (1 paper, 2016). A primary or metastatic malignant neoplasm involving the cervix. "In cervical cancers, increased MIA expression correlated strongly with the clinical stage (P = 0.0177), T classification (P = 0.0185), and lymph node metastasis (P = 0.0477)." (PMID 27145272, 2016). "Non-tumor cervical mucosal samples had negative or very weak MIA gene family expression, whereas 34.1% (43/126), 31% (39/126), and 30.2% (38/126) of cervical cancer cases exhibited cytoplasmic MIA, MIA2, and TANGO staining, respectively." (PMID 27145272, 2016). "Furthermore, MIA (P < 0.0001), MIA2 (P = 0.0144), and TANGO expression (P = 0.0151) were associated with a poor prognosis among patients with cervical cancer." (PMID 27145272, 2016).
cutaneous melanoma (1 paper, 2019). A primary melanoma arising from atypical melanocytes in the skin. "The selected candidate proteins in this study have been recently assessed in UM (i.e. OPN, MIA, CEACAM-1, MIC-1, and HSP27) and/or cutaneous melanoma as well as other cancers (i.e. SPON1 and POSTN) by either ELISA or immunohistochemistry or other techniques." (PMID 30867659, 2019).
deafness (1 paper, 2013). An inherited or acquired condition characterized by the complete loss of the ability to hear from one or both ears. "One interesting result is that a mutation in a novel putative responsible deafness gene, MIA, which is highly expressed in the inner ear, was identified in a dominant family (#4171), in the present study." (PMID 23967202, 2013).
epithelial dysplasia (1 paper, 2021). "The expression of MIA and MIA2 was analyzed immunohistochemically in 100 specimens (10 specimens with normal oral mucosa (NOM) and 30 specimens each with low-grade epithelial dysplasia (LED), high-grade epithelial dysplasia (HED), and OSCC)." (PMID 34441956, 2021). "MIA and MIA2 may therefore be novel IHC markers that enable discrimination between normal tissue and epithelial dysplasia." (PMID 34441956, 2021).
melanoma in situ (1 paper, 2021). "Previous studies confirmed that MIA is not expressed in benign melanocytes from normal skin biopsies, but MIA is reportedly expressed in some nevi and all melanoma in situ." (PMID 34441956, 2021).
migraine (1 paper, 2024). "Additionally, we detected nominally significant associations for a CNV on chromosome 19 (41,381,588–41,387,347 bp, deletion frequency = 0.054 and duplication frequency = 0.022) with the pQTL of the MIA protein level (P = 2.38 × 10–6) and migraine (ICD-10 code G43; P = 3.14 × 10–5)." (PMID 38565889, 2024).